HNRNPC (heterogeneous nuclear ribonucleoprotein C)
Diseases named in the same sentence as HNRNPC in open-access papers (continued):
Sharing a sentence is not in itself a finding about the gene and the disease.
tumor (continued). "We have not only found that hnRNPC can be deregulated in tumours driving characteristic APA profile changes but we further show that some of the affected genes are of high physiological importance for cancer progression." (PMID 31147722, 2019). "Nonetheless, validation of potential tumor markers such as hnRNPC will continue to be a major focus of HCC research in the next few years." (PMID 27565572, 2016). "SMMC-7721 is a low-grade malignant human hepatocellular cell line and hnRNPC and multinucleation are related to tumor grade." (PMID 23599772, 2013). "Heterogeneous ribonuclear protein C (hnRNPC) is an RNA-binding protein located in the nuclei of normal cells; however, it is also distributed in the cytoplasm of tumor cells." (PMID 23599772, 2013). "The results indicate a possible involvement of HNRNPC in tumor prognosis." (PMID 39735682, 2025). "In the present study, RALYL played a role in cancer inhibition through HNRNPC, which may be consistent with previous studies that HNRNPC promotes CRC progression involved in tumor growth." (PMID 40052233, 2025). "Upon growth of the tumor tissues, the subcutaneous tumors were harvested for evaluation of tumor formation in nude mice, revealing significant suppression of tumorigenic potential following HNRNPC gene knockdown in HCCLM3 cells." (PMID 39735682, 2025). "Mechanistically, hnRNPC may exert a tumor-promoting effect via mechanisms involving suppression of the Ras/MAPK signaling pathway or IL-6/STAT3 signaling, or reduction of HIF-1α expression." (PMID 38545555, 2024). "Additionally, we observed several cell-type-specific deMuts involved in the spliceosome gene set (GSEA: KEGG pathway), such as SRSF3 and HNRNPC mutants in tumor cells and DDX5 mutants in endothelial cells." (PMID 37433798, 2023). "Notably, HNRNPC expression remained a significant covariate in a Cox proportional hazards model even after controlling for other known prognostic metrics, such as tumour stage or received treatment." (PMID 37156909, 2023). "As an m6A recognition protein, HNRNPC is closely related to tumor initiation and development." (PMID 37522921, 2023). "We detected that HNRNPC expression was negatively associated with tumour stage and presence of metastasis, but not with tumour subtype." (PMID 37156909, 2023). "HNRNPC belongs to a family of HNRNPs, which are RNA‐binding proteins that participate in many aspects of nucleic acid metabolism and gene expression regulation and thus tumour development." (PMID 35277915, 2022). "Meanwhile, as markers of vascular endothelial cells and fibroblasts, CD31 and collagen I were increased after HNRNPC knockdown, indicating that HNRNPC might also modulate angiogenesis and collagen fibril organization of tumor microenvironment." (PMID 36536402, 2022). "While YTHDF2, RBM15, ZC3H13, METTL3, HNRNPC, YTHDC1 with m6a modifications had higher expression in the low risk group, indicating that they might be tumor suppressors." (PMID 36199800, 2022). "Tumour cells from mice injected with siHNRNPC‐silenced PanC‐1/NF co‐cultures had significantly decreased HNRNPC, RhoA, ROCK2 and YAP expression, suggesting that radiation resistance is mediated via HNRNPC and the downstream RhoA/ROCK2/YAP signalling pathway in PC." (PMID 35277915, 2022). "In vivo, HNRNPC knockdown inhibited the tumor growth and lung metastasis." (PMID 36536402, 2022). "Furthermore, the tumor weight and tumor volumes were inhibited after HNRNPC knockdown, which revealed that HNRNPC knockdown inhibited the tumor growth in vivo." (PMID 36536402, 2022). "Furthermore, transwell migration assay demonstrated that silencing HNRNPC decreased the metastatic ability of pRCC cells, while HNRNPC overexpression granted tumor cells much more aggressiveness." (PMID 35502201, 2022). "In addition, high levels of HNRNPC protein were related to larger tumor size, advanced TNM stage, and poor prognosis." (PMID 33937074, 2021).
tumor (continued). "According to GEPIA database, HNRNPC was reconfirmed to be upregulated in tumor samples." (PMID 33952721, 2021). "All of these results uncovered a novel tumor-boosting mechanism in BC, indicating that the circBACH2/hsa-miR-944/HNRNPC axis may serve as a promising therapeutic target in BC patients." (PMID 34952600, 2021). "Interestingly, most m6A regulator genes were differentially expressed between tumor and normal samples, except for HNRNPC." (PMID 33033522, 2020). "We elucidated that KHSRP could interact with HNRNPC and HNRNPC-mediated tumor growth and metastasis could be, at least partly, attributed to the activation of IFN-α-JAK-p-STAT1 signaling pathway, which is critical for tumorigenesis and metastasis in NSCLC." (PMID 31775888, 2019). "Importantly, we identify similar hnRNPC dependent APA profile shifts in RNA-seq data from patient derived tumour and normal colon epithelial cells." (PMID 31147722, 2019). "In addition, silencing HNRNPC inhibits the expression of miR-21 which exerts strong pro-survival effects and therefore plays an important role in tumour progression." (PMID 29899543, 2018). "To explore the correlation between HNRNPC and tumor immunity, we employed four commonly used algorithms (QUANTISEQ, MCPcounter, EPIC, and TIMER) to evaluate immune scores across different tumors and examine the association between HNRNPC expression and immune cell levels." (PMID 39735682, 2025). "However, only HNRNPC expression was correlated with tumor stages." (PMID 37469973, 2023). "Besides, comprehensive analysis indicated that the key m6A regulator, HNRNPC, is not only a novel prognostic biomarker in multiple cancers, but also regulates tumor immune microenvironment and immune checkpoints, providing a vital opportunity for developing immune targets." (PMID 37469973, 2023). "Specifically, RALYL binds to HNRNPC to promote the splicing of MNK2 into MNK2a instead of MNK2b, which consequently activates the p38 MAPK signaling pathway and inhibits tumor proliferation in CRC." (PMID 40052233, 2025). "Expression overlays of six RNA modification genes selected by the LASSO Cox model (DNMT1, DNMT3A, HNRNPC, IGF2BP2, NSUN5, and ZC3H13) demonstrated variable distribution across the tumor microenvironment." (PMID 40565233, 2025). "We observed that in tumor tissues with HNRNPC knockdown, we observed a significant reduction in the expression of CD4 and F4/80 compared to the control group with intact HNRNPC expression." (PMID 39735682, 2025). "MNK2 alternative splicing is essential for the tumor suppressive role of RALYL, along with RALYL regulating MNK2 alternative splicing via HNRNPC in CRC." (PMID 40052233, 2025). "Recently, accumulating literature indicated hnRNPC can serve as an oncogene in HCC progression, described as an elevated expression of hnRNPC in HCC tissues and a decrease of tumor growth and metastasis following hnRNPC silencing." (PMID 38545555, 2024). "We further assessed the role of hnRNPC and IQGAP3 in tumor progression by tracing the expression of key epithelial-mesenchymal transition (EMT) markers such as E-cadherin, N-cadherin, and vimentin." (PMID 35355828, 2022). "The results indicated that the expression levels of these four SFs, including NOVA1, RBM4, HNRNPC, and HNRPLL, in tumor tissues were significantly decreased, compared to those in normal tissues." (PMID 35832652, 2022). "It appeared that IGF2BP1/3, ELAVL1, HNRNPA2B1, HNRNPC, KIAA1429, RBM15, LRPPRC, FMR1, YTHDF1/2 are highly expressed in the tumor while FTO, METTL14/16, WTAP, YTHDC1 and ZC3H13 are down-regulated." (PMID 35095993, 2021). "Regarding tumor stemness, in this study, YTHDF2, HNRNPA2B1, HNRNPC, IGF2BP1, and KIAA1429 were positively correlated with tumor stemness, while FTO was negatively correlated with tumor stemness." (PMID 35003079, 2021). "The higher expression of YTHDF1, HNRNPC, IGF2BP1, VIRMA, and HNRNPA2B1, the more characteristics of tumor OV stem cells and the lower the tumor OV differentiation." (PMID 34150845, 2021).
tumor (continued). "YTHDF1, KIAA1429, HNRNPC, and METTL3 were most significantly upregulated in tumor samples, and METTL16 and METTL14 were markedly downregulated." (PMID 34975871, 2021). "We also compared the expression level of these SFs in GBM tumor tissues and adjacent normal tissues and found that 7 factors were significantly dysregulated, including HNRNPA1, HNRNPC, HNRPLL, NOVA1, SF3B1, KHDRBS2, and TIA1." (PMID 34326872, 2021). "In this prognostic signatures, high expression of RGS16, LYVE1, hnRNPC, ANP32A, and AIMP1 focus in promoting cell proliferation and tumor progression." (PMID 33329703, 2020). "For the m6A methylation readers, the expression of HNRNPC, YTHDF1, and YTHDF2 was also significantly increased in higher tumor grade and stage." (PMID 32850303, 2020). "Specifically, HNRNPC, YTHDF1, YTHDF2, METTL3, RBM15, YTHDF3, and KIAA1429 are highly expressed in tumor tissues." (PMID 32258108, 2020). "We observed DHX9 and MATR3 (in Tumor A, set 1), HNRNPC and LARP1 (in Tumor A, set 2), SRSF1 (in Tumor B, set 1 & Tumor B, set 2), SRSF6 and IGF2BP2 (Tumor B, set 2), HNRNPU (in Tumor B, set 2 & Tumor C, set 2), and FAM120A and HNRNPA2B1 (in Tumor C, set 2)." (PMID 31892958, 2020). "Furthermore, widespread expression of regulators like HNRNPC and HNRNPA2B1 supports their functional significance across diverse tumor microenvironments, while sparse or restricted expression of others suggests niche or indirect regulatory functions." (PMID 40565233, 2025). "Moreover, HNRNPC is found to regulate cancer‐specific alternative cleavage and polyadenylation in CRC and is involved in tumor progression." (PMID 40052233, 2025). "Upon surgical excision of the designated tumor tissues (one xenograft per group of each group, at Day-24 and Day-36), we proceeded to analyze the expression profiles of INTS13 and hnRNPC, alongside key markers indicative of cellular proliferation and apoptosis." (PMID 41429980, 2025). "In addition, the m6A readers, including YTHDF1/2/3, HNRNPC, HNRNPA2B1, RBMX, PRRC2A, and CPSF6, also demonstrated a higher expression in the tumor samples compared to the normal tissues." (PMID 38610981, 2024). "The results showed that ASEs up-regulated in BLCA with high-level neoplasm grade were enriched to several RBPs’ motifs, including “poly-T” motifs and polypyrimidine tract (Py-tract) sequence of HuR, CPEB4, TIA1, HNRNPC, PTBP1, RALY and ZC3H14, and motifs of PCBP2 and SNRNP70." (PMID 37810965, 2023). "YTHDC1, HNRNPC, HNRNPA2B1, YTHDF1, YTHDF2, and YTHDF3 all showed significantly high expression in ccRCC (all p-values < 0.0001) compared to the average overall gene expression in the tumour tissue." (PMID 36899967, 2023). "Besides, a significant positive correlation was observed between the expression of HNRNPC and that of SAE1 in tumor samples of both the TCGA_LIHC and ICGC_LIRI datasets (r = 0.43–0.69)." (PMID 35859792, 2022). "In terms of methylation, the expression level of ECE2 was significantly negatively correlated with HNRNPC, IGF2BP1, IGF2BP3 and RBM15, which may affect the tumor progression of LUAD by affecting the m6A methylation level." (PMID 36299451, 2022). "According to our results, tumor size (P = 0.005, HR = 1.957), tumor TNM stage (P = 0.014, HR = 1.786), and high HNRNPC expression (P = 0.039, HR = 1.637) could be regarded as independent risk factors for overall survival of HCC patients." (PMID 33937074, 2021). "Importantly, both the increased expression of hnRNPC and the concomitant APA profile changes were confirmed when RNA-seq data of patient-derived tumour and non-tumour colon samples were compared." (PMID 31147722, 2019). "However, in the remaining tumor types, no notable correlation was detected between HNRNPC expression and sex." (PMID 39735682, 2025).
tumor (continued). "Furthermore, we used RT-PCR to examine hnRNPC mRNA expression levels in 14 paired PDAC tissues and found that tumor samples had significantly higher levels of hnRNPC than adjacent noncancerous pancreatic tissues; high expression of hnRNPC was positively associated with advanced TNM stage." (PMID 35355828, 2022). "Indeed, we observed that in PDAC tumor samples, hnRNPC transcript levels were slightly higher than that in the normal control samples." (PMID 35355828, 2022). "Additionally, we identified that the levels of hnRNPC protein in PDAC tumor samples were much higher than in adjacent noncancerous pancreatic tissues using Western blot analysis." (PMID 35355828, 2022). "Accumulating evidence shows that heterogeneous nuclear ribonucleoprotein C (HNRNPC), which is mainly involved in RNA splicing, export, and translation, promotes progression and metastasis of multiple tumor types; however, the effects of HNRNPC in HCC are unknown." (PMID 33937074, 2021). "Most increased regulators in tumor cases compared to normal cases were YTHDF2 (p < 0.001), FTO (p < 0.001), YTHDC1 (p < 0.001), YTHDC2 (p < 0.001), YTHDF1 (p < 0.001), KIAA1429 (p < 0.001), METTL3 (p < 0.010), WTAP (p < 0.001), RBM15 (p < 0.001), HNRNPC (p < 0.001), and ALKBH5 (p = 0.001)." (PMID 32733931, 2020). "Importantly, the KEGG analysis unraveled that the relevant pathway of tumor malignancy, including JAK/STAT and MAPK signaling pathways, was significantly correlated with the HNRNPC low expression group, while the process of the cell cycle was correlated with HNRNPC high expression group (P < 0.05)." (PMID 34952600, 2021). "Differential expression analysis indicated that the protein expression levels of KIAA1429, RBM15, HNRNPC, HNRNPA2B1, YTHDF1, YTHDF2, and YTHDC1 were higher in tumor samples than in non-tumor samples." (PMID 32582536, 2020).
cancer (102 papers, 2016 to 2025). A tumor composed of atypical neoplastic, often pleomorphic cells that invade other tissues. "Dysregulation of HNRNPC emerges as pivotal across various cancer types, positioning it as a putative pan-cancer gene implicated in diverse malignancies." (PMID 39735682, 2025). "Ultimately, hnRNPC is indispensable for gene expression, and its dysregulation is linked to various pathologies, including cancer." (PMID 41429980, 2025). "Cox regression analysis demonstrated that higher HNRNPC expression was significantly associated with reduced overall survival (OS) in all 11 cancer types." (PMID 39735682, 2025). "hnRNPC has also been shown to be a modulator of many important oncogenic genes, including breast cancer susceptibility gene (BRCA), metastasis associated in lung denocarcinoma transcript 1 (MALAT1), and c-Myc." (PMID 35355828, 2022). "In short, HNRNPC may further influence cancer progression through gene mutation, protein phosphorylation, cancer associated fibroblasts infiltration and related molecular pathways." (PMID 35344508, 2022). "For instance, HNRNPA1 and HNRNPC showed different prognostic association in diverse cancer types, which were therefore shown by forest plot to illustrate the specific predictive effect in diverse types of cancers." (PMID 32915499, 2020). "The findings underscore HNRNPC’s potential as a potential focus of therapy and a predictive indicator of outcomes in diverse cancers, warranting further exploration to unravel its mechanistic intricacies and therapeutic potential." (PMID 39735682, 2025). "In our comprehensive analysis of survival outcomes across 11 cancer types, we evaluated the influence of HNRNPC expression on disease-specific survival (DSS), overall survival (OS), progression-free survival (PFS), and disease-free survival (DFS)." (PMID 39735682, 2025). "Previous studies have underscored the significance of HNRNPC in tumorigenesis; however, its specific role in malignant tumor progression remains inadequately characterized." (PMID 39735682, 2025). "The approach was validated by the identification of known regulators, such as TDP-43, and further revealed several splicing factors, including some with known APA functions in cancer, such as HNRNPC, SFPQ, and SRSF7." (PMID 39789319, 2025). "HNRNPC knockdown is known to promote distal polyadenylation site usage in cancer, and its expression is downregulated in excitatory neurons of C9ORF72-ALS." (PMID 39789319, 2025). "We leveraged publicly available databases, including The Cancer Genome Atlas (TCGA), to explore the potential involvement of HNRNPC across various cancers." (PMID 39735682, 2025). "Our pan-cancer expression analysis unveiled significant upregulation of HNRNPC in nearly all cancer lineages, with the exceptions of KIRP, KIPAN, KIRC, OV, and PCPG." (PMID 39735682, 2025). "On the other hand, APA-regulatory proteins, such as Nudix Hydrolase 21 (NUDT21) and heterogeneous nuclear ribonucleoproteins C (hnRNPC), play important roles in cancer." (PMID 40483535, 2025). "Crucially, the restoration of hnRNPC expression effectively reversed the anti-cancer effects observed upon INTS13 silencing, highlighting hnRNPC as a key mediator in the INTS13-driven oncogenic pathway." (PMID 41429980, 2025). "To experimentally validate this observed correlative relationship, we investigated the impact of INTS13 modulation on hnRNPC expression within primary pCCa-1 cancer cells." (PMID 41429980, 2025). "For example, hnRNPC contributes to cancer progression in metastatic colon cancer cells by altering the selection of APA sites and affecting MTHFD1L and NAP1L1 expression." (PMID 40384875, 2025). "HNRNPC has been previously identified as a potential marker for a poor prognosis in many cancers, including PCa." (PMID 38610981, 2024). "Although HNRNPC has been identified as an m6A reader in cancers, its regulatory mechanisms in ccRCC metastasis are poorly understood." (PMID 38184608, 2024).